IL6 (interleukin 6)
Diseases named in the same sentence as IL6 in open-access papers (continued):
Sharing a sentence is not in itself a finding about the gene and the disease.
tumor (continued). "From the PCR results of the risk-predictor genes, we speculated high expression levels of NR3C1 in tumor tissues and expressions of IL-6 and SRPX converged in paratumor tissues." (PMID 36675190, 2023). "Meantime, the tumor-derived IL6 and PD-L1 were down-regulated as the up-regulation of PTPRC." (PMID 37388747, 2023). "In contrast, the antibody blockade against the immune regulator PD-1 molecule on tumour-associated DCs resulted in the inhibition of NF-κB activation, and release of regulatory cytokines, such as IFN-α, IL-6, IL-8 and TNF-α, and the upregulation of co-stimulatory molecules." (PMID 36980527, 2023). "IL-6 can not only promote tumor growth and inhibit tumor cell apoptosis, but also activate NF-κB." (PMID 36765353, 2023). "Instead, IL-6 showed increasing values with grade progression, meaning that it is suitable for use both for diagnosis and for differentiating between the different types of tumor grades." (PMID 38137862, 2023). "This indicates that CAFs may influence tumor cells and other cell types via the IL-6/IL-6R pathway and a wide range of outgoing signals." (PMID 38239853, 2023). "RNA-seq and subsequent experimental analyses demonstrated that high Tagln expression in iMEFs promoted the pro-tumor phenotype of fibroblasts and increased IL-6 secretion via the activation of the NF-κB signaling pathway, by enhancing the phosphorylation of IKKβ and p65." (PMID 36990991, 2023). "In this context, interleukin-6 (IL6) and TGF-beta likely represent the best-characterized mediators of EMT, implicated in the mechanisms triggering the mesenchymal transitions at the tumor–stroma interface." (PMID 37176013, 2023). "In further support to the upregulation of key effectors for tumour surveillance, lepadin A increased synthesis of IL-6 and reduced the secretion of the immunosuppressive cytokine IL-10 in the supernatants of the co-cultures with DCs, while did not affect the levels of IL-1β and TNFα." (PMID 37779162, 2023). "Furthermore, it was shown that inhibition of IL-6 gene expression improved patient response to RT and the biological behavior of the tumor." (PMID 36930089, 2023). "Consistent with observed higher tumor growth rate, unmodified neutrophils gradually released more IL-6 and TNFα, which may lead to cytokine release syndrome in patients and require more in-depth safety studies with IL-6 blockers." (PMID 37080958, 2023). "Notably, IL-6 has been found to promote tumor cell proliferation, survival, angiogenesis, and escape from immune surveillance." (PMID 37397366, 2023). "The relation between higher IL-6 expression and unfavourable prognostic characteristics could be related to the fact that IL-6 is crucial for tumour progression from the Ta stage into the T1 stage." (PMID 37047238, 2023). "Interestingly, SC144/paclitaxel combination therapy only reduced human IL-6 levels in plasma, pointing to its direct interference with tumor IL-6 expression." (PMID 36672405, 2023). "Therefore, tumorigenic EMT seems to be promoted by a reciprocal immunosuppressive interplay between tumor cells and macrophages, activated by IL-6/JAK/STAT3 signaling during the early phases of tumor progression." (PMID 37190141, 2023). "Indeed, cytokines such as IFN-γ, IL-27, IL-23, IL-12, and IL-2 have tumor suppressor functions, whereas pro-inflammatory cytokines, including IL-1, IL-6, and tumor necrosis factor-α, have tumor-promoting." (PMID 37046658, 2023). "In addition, cytokines (e.g., tumor necrosis factor-α (TNF-α) and interleukin-6 (IL-6)) are released during tumor ICD accompanied by a strong inflammatory response." (PMID 37766117, 2023). "Previous studies indicated that IL-6 mediates cross-talk between tumor cells and CAFs in the TME." (PMID 36635302, 2023). "As indicated in the literature for other cancers, tumor secreted molecules such as IL6." (PMID 36536236, 2023).
tumor (continued). "Indeed, combined ICI and anti-IL-6 or anti-IL-6R Abs have been reported to potentially enhance anti-tumor immunity or reduce immune-related toxicity in preclinical and clinical studies." (PMID 38469154, 2023). "In turn, IL-6 promoted the migration and invasion of tumor cells." (PMID 36614179, 2023). "The results further confirmed the protumor role of IL‐6 in tumour progression." (PMID 36419386, 2023). "In addition, ONA suppressed IL-6-induced SBC-3 and SBC-5 proliferation, suggesting that ONA prevents macrophage-derived soluble factors, including IL-6, from inducing tumor proliferation." (PMID 36961655, 2023). "Activated TAM promotes tumor growth and immune tolerance through NF-κB/IL-6 pathway." (PMID 37074800, 2023). "Upregulation of IL-6 in plasma levels of mice has been shown to promote tumor growth, angiogenesis, metastasis, and the expansion of cancer stem cells, as well contribute to multidrug resistance via gp130/MAPK/STAT3-mediated activation of C/EBPβ/δ transcription factors." (PMID 38067195, 2023). "Importantly, the results of in vivo experiments show that it can significantly inhibit tumor growth by promoting tumor-associated macrophage repolarization into M1 type, releasing TNF-α and IL-6 to initiate tumor immunity." (PMID 37894410, 2023). "Specifically, the overactivation of KRAS signaling could enhance the excretion of IL-6 resulting in tumor initiation and progression." (PMID 38097680, 2023). "Also, cytokines such as IL-2 and IL-6 favor tumor proliferation, inhibit apoptosis, and participate in the conversion of non-cancerous cells to tumor stem cells." (PMID 37895359, 2023). "IL-6 (an inflammatory factor) may be from tumor cells in the peritoneal cavity, so it is often increased locally in the peritoneal cavity without significant changes in the serum." (PMID 37505161, 2023). "For instance, CML-derived exosomes suppress the cytotoxic T cells and elevate various genes including FOXP3, IL-17, and IL-6 that may stimulate the tumor-favorable T cells such as regulatory T cells." (PMID 38188673, 2023). "Irradiated tumor tissues and cancer cells recruit chemokines such as CCL22 and CXCL12 and produce a range of cytokines such as TNF-α, TGF-β, IL-1, IL-6, and GM-CSF which could recruit tumor-infiltrating lymphocytes (TILs) into radiation site." (PMID 37259456, 2023). "It highly expresses tumor necrosis factor‐α, interleukin 6 (IL‐6), inducible nitric oxide synthase, and other cytokines and is involved in immune responses, such as insulin resistance and killing intracellular parasites and tumor cells." (PMID 36840491, 2023). "IL-6 is an important cytokine, which is closely related to the malignant behavior, such as promotion of inflammation, proliferation, angiogenesis, invasion, metastasis of tumor in TME." (PMID 36816959, 2023). "MDSCs can be induced in vitro by various tumour-derived substances, including prostaglandin E2, interleukin-6, interleukin-10, interleukin-1, transforming growth factor (TGF), stem cell factor (SCF), and pro-angiogenic factors, including vascular endothelial growth factor (VEGF)." (PMID 38104117, 2023). "After incomplete LITs, IL-6 was produced by injured tumor cells and infiltrated inflammatory cells in the residual tumor, and IL-6 can in turn foster the activation and infiltration of inflammatory cells as well as the production of proinflammatory cytokines, resulting in a prolonged inflammation." (PMID 36831664, 2023). "STAT3 activation mediated by the proinflammatory cytokine IL-6 might be responsible for the expansion of MDSCs, which then accelerated tumor growth." (PMID 37234990, 2023). "While the exact molecular mechanism of action for SC144-mediated polarization of macrophages and ICD induction is beyond the scope of this work, prior literature suggests that the IL-6/gp130/STAT3 axis plays a crucial role in tumor progression and immunosuppression." (PMID 37553327, 2023).
tumor (continued). "iCAFs that are characterized with secreting abundant inflammatory factors like IL-6, IL-8 and IL-11 might participate in tumor metastasis and immune escape." (PMID 37853415, 2023). "Retinoids are known to inhibit tumor-promoting IL-6 production." (PMID 37185128, 2023). "In addition, some P2Y receptors are also implicated in the interplay between microglia and tumors, as an illustration, if selective stimulation of P2Y14 receptors on microglia reduces IL-6 secretion and even tumor cell proliferation." (PMID 37700840, 2023). "Nevertheless, these findings support a vital role of M2 macrophage polarization and a role of IL10 and IL6/STAT3 signaling in HES1 (−) KRAS mutant CRCs that may act in concert to promote tumor progression and metastasis." (PMID 37749297, 2023). "IL-6 was reported recently to also inhibit anti-CTLA4 efficacy in mouse tumor models." (PMID 36599350, 2023). "Further, directional changes in response to tumor growth differed by sex in γ-chain-utilizing and IL-6/IL-12-like cytokine interactions; many γ-chain-utilizing cytokines were downregulated in response to tumor growth in female skeletal muscle, while they were upregulated in males." (PMID 37511427, 2023). "In addition to promoting tumor angiogenesis, tumor-associated endothelial cells (TEC) can produce IL-6 through the NF-B signaling pathway and recruit MDSCs in order to assist tumor cells to avoid immune clearance." (PMID 37511228, 2023). "IL-6, a pleiotropic cytokine, is well-known for its pro-inflammatory and tumor-promoting effects." (PMID 36831664, 2023). "Initially, it has been viewed as a factor of malignancy, with the IL-6/JAK/STAT3 signaling path having effects such as anti-apoptosis, angiogenesis, and proliferation, while more recent findings have shown that IL-6 also has beneficial roles regarding anti-tumor immunity." (PMID 37892997, 2023). "IL-6 upregulates miR-253p in tumor cells by STAT3/c-MYC signaling." (PMID 36941614, 2023). "During chronic inflammation, the TME is enriched with inflammatory factors secreted by tumor cells, CAFs, and immune cells, such as IL-6, IL-8, IL-1β, IL-10, and IL-17, creating a microenvironment conducive to dormancy escape as well as reactivating cancer cell expansion." (PMID 37173977, 2023). "In cancer, the crosstalk between tumor and immune system could increase the level of pro‐inflammatory mediators such as IL‐6, which could promote skeletal muscle atrophy in multiple signaling pathways." (PMID 35848533, 2023). "Additionally, the stage of the tumor, the level of IL-6 expression, and the presence of other cytokines and signaling molecules can influence its effects." (PMID 37892997, 2023). "A complex, reciprocally regulated cytokine network induced by IL-6 in the tumor cells, including inflammatory cytokines (MCP-1, GM-CSF, and IL-8) and angiogenic factor (VEGF), results in malignant and invasive tumor growth in vivo and stimulates tumor cell proliferation and migrations." (PMID 36793738, 2023). "Furthermore, these DC/tumor fusion cells produced higher levels of TNF-α, IL-1β and IL-6 than DCs cultured alone or simply mixed with tumor cells." (PMID 37419930, 2023). "The pro-tumor functions of IL-6 are mostly through IL6-STAT3 axis which triggers up-regulation of target genes responsible for tumor cell survival, the activation of STAT3 could also block the maturation of dendritic cells (DCs) and inhibit T cell function." (PMID 36875137, 2023). "identify IL-6 as a correlate of poor clinical response to atezolizumab (anti-PD-L1) therapy and demonstrate that IL-6 impairs anti-PD-L1 efficacy by restricting the anti-tumor functions of cytotoxic T cells." (PMID 36599350, 2023). "Furthermore, it has been reported that tumor-associated macrophages promote RCC epithelial-mesenchymal transition, migration, and invasion via activating IL-6/STAT3 signaling." (PMID 37927783, 2023).
tumor (continued). "To further investigate the photosensitizing mechanism of GTW, we used Western blotting to examine the key proteins involved in NF-κB/IL-6/STAT3 signaling pathway in tumor tissues, including IL-6, NF-κB (p65), phospho-NF-κB (p-p65), STAT3, phospho-STAT3 (p-STAT3)." (PMID 37818040, 2023). "Macrophages are adept at phagocytosis, and whether their phagocytosis of live tumor cells is enhanced upon blockade of TNFα, IL-1β, or IL-6 is unknown." (PMID 37461742, 2023). "A previous study illustrated that crosstalk between tumor-promoting macrophages and the proximate vasculature creates a permissive niche for angiocrine-induced macrophage polarization driven by interleukin 6 (IL-6) and colony-stimulating factor 1 (CSF-1)." (PMID 37887354, 2023). "IL-6 may promote the mobilization of anti-tumor CD8+ effector T cell responses, the development of APC, such as DCs and cytotoxic T cells, as well as the survival, proliferation, differentiation, and recruitment of leukocytes." (PMID 36835413, 2023). "In a mouse model, subtotal tumor resection was shown to increase levels of IL-1, IL-6, and IL-10." (PMID 37568571, 2023). "Cytokines including IL-6, TGF-β could drive tumor-associated CAF phenotype and promote tumor metastasis." (PMID 36698173, 2023). "IL-6 in particular is a key factor for mediating tumor progression." (PMID 36816953, 2023). "In addition, IL-6 secretion accelerates the migration of macrophages and neutrophils in the liver, which amplifies the inflammatory response and the development of tumours." (PMID 37035153, 2023). "As a result, IL-6–Stat3 plays a role in promoting tumor growth through the Th17 response." (PMID 37764733, 2023). "Furthermore, the IL-6R-neutralizing antibody inhibited STAT3 activation induced by MpMDCS stimulation in SBC-3 cells, suggesting that MpMDCS also enhances tumor proliferation via STAT3 activation induced by the IL-6/IL-6R signaling pathway." (PMID 36961655, 2023). "By contrast IL-6 and IL-11 expression in tumor cells was decreased by suppression of YAP." (PMID 37927473, 2023). "Among these, tumor-stimulated MSCs secrete high levels of the pro-inflammatory cytokine IL-6." (PMID 36831562, 2023). "Interleukin-6 (IL-6) is a dominant player in the cytokine network, which not only promotes the differentiation of immune cells, but also plays a vital role in cytokine storm, acute lung injury and tumor immunity." (PMID 36902060, 2023). "Moreover, IL-6 was checked because it is also known tumor promoting cytokines for NASH-related HCC19." (PMID 37291206, 2023). "CAFs not only secrete high levels of IL-6 but also promote IL-6 secretion from tumour cells." (PMID 37927475, 2023). "Furthermore, IHC staining revealed that the increased expression of Ki67 and CD44 (invasive marker) and the elevated infiltration of F4/80+ macrophages in cSERPINE2 overexpressing tumor tissues were blocked by anti-IL-6 antibody." (PMID 36797769, 2023). "Furthermore, IL-6 mediates the crosstalk between tumor cells and CAFs by supporting tumor growth and promoting fibroblast activation." (PMID 38193080, 2023). "Interestingly, ID1 expression leads to IL-6 production, activating STAT3, which is known to drive tumor associated macrophages toward an immunosuppressive phenotype, also promoting angiogenesis, invasion and epithelial-mesenchymal transition (EMT)." (PMID 38028629, 2023). "Here, we showed that CAFs in the glucose-starved PDAC TME utilized lactate from LDHA-active glycolytic tumor cells as an energy source to support proliferation and interleukin-6 (IL-6) production, which suppressed antitumor immune cells and accelerated PDAC tumor progression." (PMID 37733442, 2023). "Furthermore, the farnesoid X receptor (FXR), that is usually downregulated in iCCA cell lines and human samples, has been shown to act as a metastasis suppressor in this tumor by inhibiting IL-6-induced EMT." (PMID 38275386, 2023). "IL-6 was also shown to enhance the proliferation and anti-tumor activity of CAR-Ts." (PMID 37298069, 2023).
tumor (continued). "Furthermore, they have previously shown tumor cell-derived IL1α induces stromal-derived IL-6, reciprocally activating tumor cell-autonomous STAT3 signaling, a well-known indicator of chemoresistance and oncogenic signaling in PDAC." (PMID 36902166, 2023). "Interestingly, FRA-1 controls the IL6 transcription not only in neoplastic cells but also in macrophages recruited by paracrine signals to the tumor microenvironment, in which the TAMs represent a major source of IL6." (PMID 37176013, 2023). "IL-6 assists tumor cells’ survival with TME manipulation as well as downregulation of CD8+ T cells, macrophage M1 to M2 phenotype changes and upregulation of immune-suppressing cells such as T helper 17 (Th17), Tregs, and myeloid-derived suppressive cells (MDSCs)." (PMID 36899885, 2023). "Besides, HCC-derived TGF-β increased the expression of TIM-3 on TAMs, which enhanced tumor immune tolerance and stimulated tumor growth via NF-κB/IL-6 pathway." (PMID 37007125, 2023). "Furthermore, previous studies have shown that miR-25-3p secreted by tumor cells promotes IL-6 secretion in TAMs through exosomes." (PMID 36941614, 2023). "The time-dependent and dosage-specific effects of sorafenib on tumor invasion may be due to differences in the regulation pattern of the effect of IL-6 on HIF-1α, namely, positive regulation in the early stage and negative regulation in the later stage." (PMID 37476196, 2023). "Notably, TERT deficiency and dysfunctional telomeres reduced peripheral IL6 and TNF levels, as well as expression of inflammation and tumor immunosuppression markers Tnf, Ifng, IL10 and PD-1 upon LLC challenge." (PMID 37085672, 2023). "TNF-α and IL-1 secreted by macrophages are strong stimulators of IL-6 produced by tumor cells." (PMID 37151385, 2023). "Moreover, M2-TAMs play a crucial role in tumour progression due to their influence on epithelial-mesenchymal transition (EMT) of the primary tumour by means of in-inflammatory cytokines and growth factors, such as IL-6, IL-10, and TGFβ." (PMID 36857852, 2023). "Authors postulated that differential expression of Annexin-A1, as a function of HPV status, may reflect attempts to regulate expression of pro-inflammatory cytokines (e.g., IL-6) in tumor cells." (PMID 37954869, 2023). "As IL-6/gp130/STAT3 activation is associated with immunosuppressive TAMCs, including tumor-associated macrophages, we examined whether SC144 can influence M1/M2 polarization of macrophages in vitro." (PMID 37553327, 2023). "In addition, it has been studied that Tumor cells can secrete cytokines and growth factors such as IL-6 or SDF-1 that can activate TGF-β secretion by MSC." (PMID 36966336, 2023). "On the other hand, in certain situations, IL-6 can stimulate an anti-tumor immune response." (PMID 37892997, 2023). "Within the tumor microenvironment, cancer cell interactions with adipocytes and macrophages promote cancer progression through a variety of mechanisms involving oxidative stress, IL-6, IL-1β, STAT3, ERK and CLS." (PMID 36670988, 2023). "On one hand, elafin was related to an unfavorable prognosis of OC patients which involved apoptosis of tumor cells and the IL-6/JAK/STAT3 signaling pathway; on the other hand, a high expression of elafin participated in immunotherapy for tumors, indicating an ideal survival situation." (PMID 36742380, 2023). "Compared to OV-mOX40L or neutralizing antibody treatment alone, the combination therapy of OV-mOX40L with anti-IL6 or anti-PD-1 antibody significantly delayed tumor growth, and the most effective tumor inhibition was observed with the triple therapy (OV-mOX40L+anti-IL6+anti-PD-1)." (PMID 37554264, 2023). "In addition, IL-6 limits anti-tumor T-cell responses by promoting the differentiation of M2 macrophages or acting on dendritic cells to inhibit the expression of MHC-II, CD80/86, and IL-12 and promote IL-10 production." (PMID 38026978, 2023).